RUNX1 (RUNX family transcription factor 1)
Diseases named in the same sentence as RUNX1 in open-access papers (continued):
Sharing a sentence is not in itself a finding about the gene and the disease.
leukemia (continued). "Our hypothesis is a mutant RUNX1 with a significantly higher DNA-binding affinity could overcome leukemia-RUNX1 mutations and restore RUNX1-mediated hematopoiesis." (PMID 31048839, 2019). "In summary, isothermal titration calorimetry (ITC) investigation of DNA-binding ability of the WT and clinical mutations of RUNX1 quantitatively confirms results from earlier research, showing that DNA-binding of the leukemia-relevant mutant RUNX1 is significantly decreased or lost." (PMID 31048839, 2019). "KAT6B has been shown to be transcriptional coregulator that physically and functionally interacts with the Runt-related transcription factor 1 (RUNX1), a recurrent leukemia-associated target, and the nuclear receptor peroxisome proliferator-activated receptor-α (PPARα) to exert its role." (PMID 30041677, 2018). "RUNX1 is a recurrently mutated gene in sporadic myelodysplastic syndrome and leukemia." (PMID 29326930, 2017). "Moreover, RUNX1 is required for definitive hematopoiesis, yet its loss of function is associated with leukemias." (PMID 29033978, 2017). "However, it is likely that inherited RUNX1 mutations play a more active role in promoting leukemia progression." (PMID 29326930, 2017). "Loss of wildtype CBFβ is expected to allow more RUNX1 to act in complexes with the fusion protein or with other transcription factors, and perhaps the activity of these other complexes accelerates the development of leukemia." (PMID 27542261, 2016). "RUNX1 is one of the most frequently mutated genes in human leukemia." (PMID 26745853, 2016). "RUNX1/AML1 is among the most commonly mutated genes in human leukemia." (PMID 26745853, 2016). "However, RUNX1-ETO9a causes accelerated leukemia development in mice and its expression is correlated with worse survival in patients." (PMID 27542261, 2016). "In megakaryocytic cells, MYL9 expression is regulated by RUNX1, a major hematopoietic transcription factor whose haplo-deficiency is associated with familial thrombocytopenia, platelet dysfunction, and predisposition to leukemia." (PMID 26910538, 2016). "However, a certain level of RUNX1 activity was required for the growth and survival of AML1-ETO and MLL-AF9 AML cells and combined loss of Runx1/Cbfb inhibited leukemia development induced by MLL-AF9." (PMID 25914884, 2015). "In addition, RUNX1 loss-of-function mutations are associated with leukemia, as well as with Familial Platelet Disorder with propensity to develop AML (FPD/AML)." (PMID 26483790, 2015). "In addition to somatic alterations, germ-line point mutations in RUNX1 are responsible for an autosomal dominant platelet disorder with a propensity to develop leukemia (FPD-AML, OMIM 601399)." (PMID 18671852, 2008). "Additionally MYST4 can interact with RUNX1 (Runt-related transcription factor 1), a recurrent leukemia associated target." (PMID 17980037, 2007). "Finally, DYRK1A could play a potential role in the regulation of other Hsa21-encoded genes implicated in DS-associated leukemias, like RUNX1 and RCAN1." (PMID 40519271, 2025). "Moreover, only CBFβ-SMMHC variants able to enhance the DNA binding affinity by RUNX1 could induce leukemia in mouse models." (PMID 40763310, 2025). "We then hypothesized that the AMP population observed in Runx1+/R188QMx1-CreCbfb+/56M mice is functionally different from that observed in Mx1-CreCbfb+/56M mice with loss of leukemia-initiating ability, similar to that observed in Runx1fl/flMx1-CreCbfb+/56M mice." (PMID 40763310, 2025). "Given that germline mutations of RUNX1 or ETV6 are associated with leukemia with incomplete penetrance, these data suggest somatic alterations of these genes also require additional mutations for leukemia development, which may cooperatively define the immature leukemic phenotypes." (PMID 38212634, 2024).
leukemia (continued). "Expression of AF4-MLL alone caused B-/T-type leukemia, but only in one-third of the transplanted mice, which may indicate that other transcription factors (e.g., RUNX1) were somehow complementing functions deriving from the missing MLL-AF4 allele to drive leukemia." (PMID 34489550, 2021). "In leukemia-associated genomic rearrangements, RUNX1 may either represent a C-terminal fusion partner—for example, in ETV6-RUNX1-positive B-ALL—or it may be N-terminally fused to proteins, such as eight-twenty-one family members (RUNX1T1, CBFA2T2, CBFA2T3) in AML." (PMID 34299194, 2021). "In addition, upregulation of MPL expression cooperates with RUNX1‐ETO to cause leukaemia in mice." (PMID 34766123, 2020). "In addition, we hypothesize that a “good” mutant RUNX1 with a higher binding affinity to DNA could counteract a leukemia-causing RUNX1 mutant and have an enhanced RUNX1 activity for hematopoiesis." (PMID 31048839, 2019). "Thus, the beneficial RUNX1 mutant could counteract a leukemia-causing RUNX1 that reduces the amount of CBFβ." (PMID 31048839, 2019). "Leukemia-associated cohesion mutations have been found to impair differentiation and enforce stem cell programs in human stem and progenitor cells by demonstrating increased chromatin accessibility of stem cell regulators like the Runt-related transcription factor 1 (RUNX1) and GATA2." (PMID 27723796, 2016). "RUNX1, which plays a role in hematopoietic development through specifying the hematopoietic stem cell, has been studied extensively in leukemia due to chromosome 21 to chromosome 8 translocation that is often found in leukemia, but is by itself insufficient to cause leukemia in mouse models." (PMID 25993293, 2015). "Finally, we showed that the predisposition of FPD-AML to develop leukemia may be due to an increased rate of mutation in RUNX1 heterozygous cells." (PMID 18671852, 2008). "We performed mass spectrometry to determine if HDAC1 activity influences the recruitment of proteins to the RUNX1 complex in leukemia cells." (PMID 41214140, 2026). "We confirmed the interaction by showing higher co-immunoprecipitation of PTBP1 with RUNX1, compared to IgG, in 3 independent mouse CM+ leukemia samples." (PMID 41214140, 2026). "Our study demonstrates a novel facet of RUNX1’s role in leukemia through its interaction with PTBP1 and the regulation of metabolism." (PMID 41214140, 2026). "Previous work from our lab showed that HDAC1 is required for active transcription of a subset of RUNX1 target genes in leukemia cells." (PMID 41214140, 2026). "Collectively, our results provide new insights into the intricacies of co-transcriptional splicing in leukemia and hematopoiesis, further underscoring the central role RUNX1 plays in both these processes." (PMID 41214140, 2026). "RUNX1 is known to have roles in both leukemia and healthy hematopoietic stem and progenitor cells (HSPCs)." (PMID 41214140, 2026). "We also performed immunoprecipitations/westerns (IP/WB) using the human CM expressing AML cell line, ME-1, and found that RUNX1 interacts with PTBP1 in human leukemia cells, as well." (PMID 41214140, 2026). "The lower RUNX1 chromatin binding seems to correlate with longer latency for leukemia development in the Mx1-CreCbfb+/56M-ΔHABD mice." (PMID 40763310, 2025). "Along with other recent findings, these data challenged the RUNX1-repression model and underscore the essential role of RUNX1 in CBFB-MYH11–driven leukemia development." (PMID 40763310, 2025). "The ETV6::RUNX1 fusion acts as a weak oncogene and is insufficient to initiate leukemia independently." (PMID 40634509, 2025). "For the leukemia patients harboring ETV6::RUNX1, an aberrancy in the CLP–pre-pro-B–early-pro-B differentiation axis was observed." (PMID 39945785, 2025). "Modeling approaches of ETV6::RUNX1+ preleukemia and overt leukemia in mice were largely unable to reproduce restriction to B lineage leukemia seen in humans." (PMID 40177616, 2025).
leukemia (continued). "Collectively, these results suggest that the AMP cells in Runx1+/R188QMx1-CreCbfb+/56M mice had lower leukemia potential, further confirming that DNA binding by RUNX1 is required for the generation and maintenance of functional AMP population for leukemia." (PMID 40763310, 2025). "In twins with concordant ETV6::RUNX1-positive leukemia, ALL develops at different times, and postnatal latency can be protracted." (PMID 40243620, 2025). "In this study, we used multiomic data from ETV6::RUNX1 leukemias to identify genomic features predictive of therapy response at disease presentation." (PMID 40634509, 2025). "Although previous studies have suggested that the leukemic fusion protein AML1-ETO blocks differentiation by dysregulating RUNX1 target genes, recent data actually suggest a positive role for RUNX1 in leukemia." (PMID 39450904, 2025). "The four most common leukemia genes in B-ALL children were ETV6/RUNX1, E2A/PBX1, MLL, and BCR/ABL in sequence." (PMID 41195225, 2025). "One remaining question is how RUNX1 functions in combination with other key transcription factors in these various types of leukemia." (PMID 39450904, 2025). "In a study of mixed-phenotype acute leukemias, single-cell multi-omics analysis inferred a transcription factor, RUNX1, that influences leukemia survival." (PMID 40283301, 2025). "To date, MRD level is the only identified biomarker that predicts treatment failure in ETV6::RUNX1 leukemia." (PMID 40634509, 2025). "The reported prevalence of the ETV6::RUNX1 fusion was about 100× higher than the actual leukemia incidence, indicating that the fusion gene is only mildly oncogeneic." (PMID 40243620, 2025). "The pathogenesis of these leukemias critically involves an interaction between the transcription factors RUNX1 and CBFB, which represents a promising target for new targeted therapies." (PMID 41155189, 2025). "To investigate the impact of RUNX1-R188Q on Cbfb-MYH11–induced leukemia, we examined the AMP population in the bone marrow, as this cell population plays a critical role in Cbfb-MYH11–induced leukemia." (PMID 40763310, 2025). "This analysis revealed that cluster c0, enriched in AMP cells from Runx1+/R188QMx1-CreCbfb+/56M mice, represents an early stage of leukemia development." (PMID 40763310, 2025). "In AML1-ETO leukemia, genomic data have suggested a functional complex among RUNX1, LDB1/LMO2, and HEB." (PMID 39450904, 2025). "In scRNA-seq data from five ETV6::RUNX1 leukemias from our previous study, A3B expression was the highest in the G2M phase cells compared to other cell cycle phases." (PMID 40634509, 2025). "ETV6::RUNX1 leukemia is the second most common subtype of childhood B cell acute lymphoblastic leukemia (B-ALL)." (PMID 40634509, 2025). "Earlier study reported that APOBEC signatures (SBS2 and SBS13) were enriched in ETV6::RUNX1 leukemia." (PMID 40634509, 2025). "Partial tandem duplications of RUNX1 on chr21 were found, specifically in myeloid leukemia-DS samples, presenting its essential role in DS leukemia progression." (PMID 41381484, 2025). "A large diversity offusion oncogenes was observed, primarily in one tumor, the three most commonbeing: EWSR1::Fli1 (n = 13) observed in Ewing sarcomas, PAX3::FOXO1 (n = 12) inrhabdomyosarcomas, and ETV6::RUNX1 (n = 8) in childhood leukemias." (PMID 40093400, 2025). "Consistent with previous studies in ALL, our findings showed that the APOBEC mutational signatures (C → T and C → G conversions) are prevalent in ETV6::RUNX1 leukemia." (PMID 40634509, 2025). "All together, these results suggest that enhancing RUNX1’s DNA binding affinity is a critical step for CBFβ-SMMHC-induced leukemia." (PMID 40763310, 2025).
leukemia (continued). "The recent studies strongly suggest that wild‐type RUNX1 is required for the proliferation and survival of certain types of leukemia cells." (PMID 40171874, 2025). "Overall, our findings highlight SNV, CNV, and transcriptomic alterations impacting the induction and consolidation treatment response among patients with ETV6::RUNX1 leukemia paving the way for more tailored therapy allocation." (PMID 40634509, 2025). "RUNX1 is a key regulator in hematopoiesis, a common target of multiple chromosome translocations in human leukemia, and it plays an important role in hematopoiesis regulation and the occurrence and development of hematological malignancies." (PMID 38172714, 2024). "RUNX1 is also frequently mutated in leukemia and for example, it is fused to the corepressor eight-twenty-one (ETO) generating the oncofusion protein AML1/ETO in acute myeloid leukemia (AML)." (PMID 39680066, 2024). "The authors showed that ChREBP promotes the differentiation of leukemia-initiating cells (LICs) via the TXNIP/RUNX1 pathways." (PMID 39518998, 2024). "Ro5-3335, a small-molecule inhibitor (SMI) developed to target the RUNX1-CBFβ interaction, can treat leukemia by blocking the RUNX1/CBFβ transactivation." (PMID 38286983, 2024). "RUNX1 is known to activate the Wnt/β-catenin pathway in leukemia, facilitating the transformation of malignant stem cells." (PMID 39309442, 2024). "RUNX1 plays an important role during leukemogenesis and RUNX1 is required for leukemia development by both RUNX1-RUNX1T1 and CBFB-MYH160." (PMID 39284834, 2024). "Various novel therapeutic strategies for treating RUNX1-ETO leukemia have demonstrated promise in either clinical or experimental investigations." (PMID 38702444, 2024). "The ELN also stipulates suitable molecular biomarkers, highlighting leukemia initiating variants (e.g., NPM1, CBFB::MYH11, RUNX1::RUNX1T1, PML::RARA) essential in disease monitoring." (PMID 38891959, 2024). "On one hand, RUNX1 is part of the AML1-ETO fusion protein, which can directly inhibit the transcription of tumor suppressor genes dependent on RUNX1, disrupting normal hematopoietic cell differentiation and promoting leukemia development." (PMID 38671491, 2024). "The incidence of detectable pre-leukemia in asymptomatic children is many times that of the incidence of overt childhood BCP-ALL; for example, ETV6::RUNX1+ pre-leukemia is approximately 100-500x more common than ETV6::RUNX1+ BCP-ALL." (PMID 36959797, 2023). "RUNX1/ETO represents an excellent example of a leukaemia-specific gene that can be targeted by RNAi-based approaches." (PMID 36823395, 2023). "This means that the cytokine profile seems to be quite specific to those children, who had developed an ETV6::RUNX1-positive leukemia and seems to be influenced by factors other than environmental factors." (PMID 36741356, 2023). "Therefore, RUNX1 mutation may play an important role in the transformation of EMS to leukemia." (PMID 36930401, 2023). "For example, a study tested the effect of midostaurin in leukemia patients with RUNX1 showed a limited role of the drug in leukemia control." (PMID 38007419, 2023). "For example, inhibition of TALE family homeodomain factor MEIS2 delayed the growth of RUNX1-ETO-positive leukemia cells." (PMID 37393343, 2023). "Alterations in RUNX1 (AML1) were also restricted to Early-Pro leukemias (n = 8/23, 35%; P = 0.0018)." (PMID 37337105, 2023).
leukemia (continued). "Overall, our results suggest that IGF2BP1 plays an important role in the pathogenesis of ETV6::RUNX1 leukemia through multiple oncogenic pathways and can be utilized as an ideal therapeutic target for this particular subtype." (PMID 37670323, 2023). "These pathways were also specifically enriched in the transcriptome of ETV6::RUNX1 positive patients indicating a critical role for IGF2BP1 in this leukemia subtype." (PMID 37670323, 2023). "Genes USP42 and RUNX1 are both studied in leukemia for their involvement in chromosomal translocations." (PMID 37628680, 2023). "NRAS and also ASXL1, RUNX1, and SETBP1 gene mutations were proved to be independent risk factors for inferior OS and the increased risk of MDS progression to leukemia." (PMID 36982819, 2023). "Western blot analysis using an antibody targeting the human RUNX1 protein confirmed that the leukemias were positive for the E::R fusion protein." (PMID 38136366, 2023). "Because RUNX1 is commonly mutated in AML, it is possible that RUNX1 loss contributes to leukemia pathogenesis by increasing IL-3RA expression." (PMID 37581927, 2023). "With many of these pathways being druggable and a small molecule inhibitor for IGF2BP1 available, our work lays the foundation for novel combinatorial therapeutic approaches in ETV6::RUNX1 positive leukemias." (PMID 37670323, 2023). "The survival of leukemia cells was sensitive to PHF6 depletion in both RUNX1-ETO9a (RE9a) and MLL-AF9 (MA9) AML mouse models and in human AML cell lines." (PMID 37393343, 2023). "Our data on leukemia and epithelial cancer cell lines showed RUNX1 regulates global H3K27ac levels and thus has the potential to co-bind with other oncogenic factors at H3K27ac marked enhancers." (PMID 37213235, 2023). "The pathogenicity of RUNX1 variants was initially linked to FPD‐MM phenotype, but the discovery of new variants through the expansion of genetic explorations in leukaemia is questioning this assertion." (PMID 36819173, 2023). "In both IR1 and IR2 RUNX1 knockdown has resulted in marginal reduction of cell viability, as RUNX1 WT is known to promote cell proliferation in leukemia." (PMID 37903788, 2023). "Several genes lying within the so-called Down syndrome critical region (DSCR) at 21q22—including RUNX1 and DYRK1A—are thought to contribute to such enhanced risk to leukemias." (PMID 37670378, 2023). "These three predisposition genes harbor point mutations and small indels (both somatic and inherited), resulting in leukemia, in addition to partial or whole gene deletions being observed in RUNX1 and GATA2-driven HM." (PMID 37377909, 2023). "We developed a zebrafish model for E::R leukemia using CRISPR/Cas9 to introduce the human RUNX1 gene into zebrafish etv6 intron 5, resulting in E::R fusion gene expression controlled by the endogenous etv6 promoter." (PMID 38136366, 2023). "The transcription factor RUNX1 regulates expression of genes that inhibit leukaemia and breast cancer cells." (PMID 37542170, 2023). "Since the alteration of Runx1 gene results in the leukemia, it is widely accepted that Runx1 is involved in cell proliferation." (PMID 38040660, 2023). "For example, the small molecule inhibitor AI-10-49 selectively disrupted the interaction between the aberrant activator CBF-β and DNA binding transcriptional factor RUNX1, thereby restoring normal expression patterns and delaying leukemia progression in mice." (PMID 37297004, 2023). "In this review, we summarize the current knowledge on RUNX1 activities outside blood/leukemia, while suggesting for the first time their potential relation to specific Trisomy 21 co-occurring conditions." (PMID 37670378, 2023). "It has been shown that the leukaemia-specific fusion oncoprotein RUNX1/RUNX1T1 represses the expression of NTAL." (PMID 36902005, 2023).